IL6 (interleukin 6)
Diseases named in the same sentence as IL6 in open-access papers (continued):
Sharing a sentence is not in itself a finding about the gene and the disease.
endothelial dysfunction (922 papers, 2005 to 2026). In vascular diseases, endothelial dysfunction is a systemic pathological state of the endothelium (the inner lining of blood vessels) and can be broadly defined as an imbalance between vasodilating and vasoconstricting substances produced by (or acting on) the endothelium. "From a pathophysiologic perspective, CRP elevation reflects underlying myocyte injury, IL-6–mediated hepatic acute-phase response, endothelial dysfunction, and fibrotic remodeling." (PMID 41596517, 2026). "Systemic inflammation marked by elevated levels of CRP, TNF-α, and IL-6 has been linked to increased vascular stiffness and endothelial dysfunction, which tend to elevate systolic pressure more than diastolic." (PMID 40584971, 2025). "The elevated IL-6 levels in these patients likely contribute to the hypercoagulable state, exacerbating endothelial dysfunction and thrombosis, as high IL-6 are associated with higher cardiovascular disease risk." (PMID 40285011, 2025). "Particularly, IL-6 is highly pro-atherogenic; elevated IL-6 levels are linked to arterial inflammation and endothelial dysfunction." (PMID 40937212, 2025). "Tumor-secreted pro-inflammatory cytokines, such as IL-1β and IL-6, exacerbate endothelial dysfunction and vascular inflammation, further predisposing patients to CVD." (PMID 40227756, 2025). "Studies suggest that inflammatory cytokines such as interleukin-6 and tumor necrosis factor-alpha contribute to endothelial dysfunction and platelet activation, thereby increasing thrombotic risk." (PMID 41301451, 2025). "Studies have shown that PM2.5 exposure is associated with endothelial dysfunction and increased levels of pro-inflammatory cytokines such as IL-6 and TNF-α, which can exacerbate joint degeneration." (PMID 41170480, 2025). "This antagonism suppresses the production of pro-inflammatory cytokines like TNF-α and IL-6, which are implicated in endothelial dysfunction and vascular impairment associated with ED." (PMID 40005617, 2025). "The metabolically active fat in this region secretes proinflammatory cytokines such as IL-6 and adipokines, which impair glucose metabolism and elevate cardiovascular risk by promoting hepatic gluconeogenesis, dyslipidemia, and endothelial dysfunction." (PMID 41155098, 2025). "Key proinflammatory cytokines, including Tumor Necrosis Factor- Alpha (TNF-α), Interleukin (IL) IL-6, and IL-17, contribute to endothelial dysfunction and oxidative stress, exacerbating cardiovascular risk." (PMID 40937212, 2025). "Interleukin-6 (IL-6), another proinflammatory cytokine secreted by activated leukocytes, influences vascular contractility and is linked to endothelial dysfunction and hypertension in PE." (PMID 41303573, 2025). "Pollutants like Particulate matter smaller than 2.5 microns can cause the body to produce interleukins (IL-6, IL-1β), which can contribute to endothelial dysfunction, a common sign of preeclampsia." (PMID 41289532, 2025). "Chronic elevation of IL-6 is associated with enhanced inflammation and endothelial dysfunction, a condition wherein the endothelial cells lining the blood vessels become impaired." (PMID 41150802, 2025). "In previous studies, IL-6 has been implicated in endothelial dysfunction, vascular inflammation, and acute coronary events, supporting its potential as a biomarker." (PMID 40265387, 2025). "IL‐6 also increases the risk of CVD through endothelial dysfunction by inducing CRP synthesis in the liver, which provokes leukocytes recruitment and perpetuates inflammatory responses." (PMID 39160453, 2024). "Concurrently, systemic inflammation, evidenced by NLRP3 overexpression and elevated levels of IL-6, sCD40-L, and C-reactive protein, was associated with endothelial dysfunction biomarkers and increased in post-COVID patients with impaired gas exchange." (PMID 38867241, 2024).
endothelial dysfunction (continued). "In our previous study, circulating endothelial microparticles in LCPD were found to be the reason for endothelial dysfunction and were closely associated with plasma IL-6 concentration." (PMID 38195507, 2024). "Endothelial dysfunction induces the production of proinflammatory molecules interleukin-6 (IL-6) and tumor necrosis factor-α, which cause vasculature impairment indirectly by enhancing C-reactive protein synthesis." (PMID 39201390, 2024). "We have demonstrated through in vitro experiments that IL-6 intervention in HUVECs can cause changes in the expression levels of endothelial dysfunction markers ICAM-1 and ZO-1 ——an increase in ICAM-1 expression and a decrease in ZO-1 expression." (PMID 38195507, 2024). "On the other hand, cerebral ischemia/reperfusion-induced endothelial dysfunction in rat mesenteric resistance arteries is associated with increased plasma levels of IL-6 and COX activation." (PMID 36536168, 2024). "PAH is characterized by endothelial dysfunction and subsequent remodeling of the pulmonary vasculature, which has been linked to the pro-inflammatory cytokine IL-6." (PMID 38193997, 2024). "IL6 signaling contributes to endothelial dysfunction, and serum elevated levels are associated with disease severity." (PMID 38474287, 2024). "In a subset of the Nurses’ Health Study, the MD was linked to reduced inflammation markers (IL-6 and C-reactive protein) and endothelial dysfunction, even after adjusting for traditional CVD risk factors." (PMID 38042258, 2023). "Studies in the literature also link IL-6 to the endothelial dysfunction associated with angiotensin-II-induced hypertension." (PMID 37629496, 2023). "In PE, elevated IL-6 levels have been linked to endothelial dysfunction and poor placental development." (PMID 37700972, 2023). "MR-proADM also showed a strong correlation with systemic inflammation markers such as CRP, IL6, and TNFα, as well as significant associations with endothelial dysfunction biomarkers (SDMA, ADMA, and C-CTproET1)." (PMID 37626802, 2023). "One study observed that in vitro infusion of AngII in mouse models resulted in dose-dependent progression of endothelial dysfunction, which was associated with an increase in IL-6 and macrophage count." (PMID 37238657, 2023). "Hypertension has been associated with endothelial dysfunction and a proinflammatory state i.e. higher Angiotensin II levels, chemokines, and cytokines, including interleukin-6 (IL-6) and tumor necrosis factor-α (TNF-α)." (PMID 36251715, 2022). "IL-6 can cause endothelial dysfunction, increase peripheral vascular resistance, aggravate the occurrence of inflammatory factors, and ultimately cause damage to blood vessels." (PMID 35813436, 2022). "Although cytokines exert their pathogenic effects through the mechanisms related to endothelial dysfunction, IL-6 increases vascular permeability and promotes the secretion of pro-inflammatory cytokines by endothelial cells, amplifying cytokine release." (PMID 36556051, 2022). "Significant correlations were noted between resistin levels and all the investigated inflammatory and endothelial dysfunction markers, although the strength of the association was greater for IL-6 and sVCAM." (PMID 34496965, 2021). "In psoriasis, proinflammatory cytokines such as tumor necrosis factor-alpha (TNF-α) and interleukin (IL)-6 induce endothelial dysfunction, thereby increasing the risk of cardiovascular disease and increasing the incidence of cerebral ischemic disease." (PMID 33322823, 2020). "YKL-40 is shown to be linked to inflammation, endothelial dysfunction and tissue remodeling secreted by various cells and is also considered to be stimulated by cytokines such as interleukin-6 (IL-6)." (PMID 32895666, 2020). "Elevation of TNF-α and IL-6 expression are linked to increased oxidative stress, endothelial dysfunction and renal fibrosis." (PMID 32292787, 2020).
endothelial dysfunction (continued). "IL-6 levels are highly correlated with CVD risk, and targeting IL-6 activity with tocilizumab has been shown to improve indices of endothelial dysfunction in participants at high risk for CVD." (PMID 33089035, 2020). "In an IL-10-deficient mouse model, age-associated endothelial dysfunction occurs earlier with IL-10 deficiency, and IL-10 protected the age-associated increase in the expression of IL-6, a pro-inflammatory cytokine." (PMID 32824387, 2020). "Similar to our study, a multi-ethnic cohort study showed that a Western type of dietary pattern rich in meat, processed meat, and sweets had a positive association with CRP levels, interleukin-6, and endothelial dysfunction." (PMID 31480674, 2019). "TNF-α and IL-6 are inflammatory cytokines, released from peri-visceral fat and found to be associated with IR, endothelial dysfunction and atherogenesis." (PMID 30635365, 2019). "We additionally assessed the association between IL–6, sCD163 and cIMT with endothelial dysfunction in separate multivariate linear regression models, controlling for cIMT, among virally suppressed HIV–infected participants only." (PMID 29771268, 2018). "In a subsample of the Nurse’health Study, a Mediterranean diet index score was inversely associated with circulating CRP and IL-6, as well as markers of endothelial dysfunction (the adhesion molecules sICAM-1, sVCAM-1, and soluble E-selectin)." (PMID 30036988, 2018). "Taken together, the findings indicated that the presence of IL-6 or TNF-α in diabetic mice was associated with the reduced phosphorylation of eNOS-mediated endothelial dysfunction." (PMID 29095915, 2017). "Angiotensin II impairs endothelial function via increases in vascular superoxide and reductions in nitric oxide bioavailability and deficiency of IL-6 protects against angiotensin II-induced endothelial dysfunction and increases in vascular superoxide." (PMID 29186034, 2017). "Serum IL-6 correlates with endothelial dysfunction in human, while elevated levels of IL-6 are associated with prolonged ventilator weaning times and increased mortality in patients with AKI and acute lung injury." (PMID 26707802, 2015). "EAT has various endocrine and inflammatory functions and produce mediators such as interleukin-6, interleukin-1b, tumor necrosis factor-α and monocyte chemotactic protein-1, which can cause endothelial dysfunction." (PMID 24872849, 2014). "Increased plasma concentrations of interleukin-6 (IL-6) and other inflammatory cytokines have been associated with the presence of endothelial dysfunction in obese patients." (PMID 24138787, 2013). "PTH stimulates vascular smooth muscle cells to produce factors involved in sclerosis, and induces the endothelial expression of factors implicated in endothelial dysfunction, such as endothelin-1 and interleukin-6." (PMID 22937036, 2012). "Increased levels of IL-6 at delivery have been reported in pre-eclampsia, indicating that IL-6 can be harmful, possibly playing a role in the inflammation and endothelial dysfunction associated with pre-eclampsia." (PMID 23155405, 2012). "Consistent with this idea, it was observed that IL-6 deficiency protects against Ang II – induced endothelial dysfunction." (PMID 19936194, 2008). "Elevated IL6 in cardiovascular disease may be associated with activation of the inflammatory pathway, endothelial dysfunction, and epigenetic regulation." (PMID 40650062, 2025). "Compared with healthy controls, IL-6 levels are increased in the blood of LCPD patients, and IL-6 produces endothelial microparticles (EMPs) by stimulating endothelial cells, thus leading to endothelial dysfunction, which may be a cause of LCPD." (PMID 40041162, 2025). "If a true association exists, tumor-derived cytokines such as interleukin-6 and vascular endothelial growth factor could conceivably damage the earlobe microcirculation by promoting systemic inflammation, angiogenesis, and endothelial dysfunction." (PMID 40734893, 2025).
endothelial dysfunction (continued). "Adipose tissue, in particular the visceral fat, is an active endocrine organ that secretes pro-inflammatory cytokines such as tumour necrosis factor-alpha (TNF-α) and interleukin-6 (IL-6), both of which have been implicated in endothelial dysfunction and venous wall degeneration." (PMID 40261445, 2025). "Moreover, changes in cytokine levels, such as IL-6 (interleukin 6), IL-10 (interleukin 10), and IL-13 (interleukin 13), are associated with treatment-related toxicities, notably fatigue and endothelial dysfunction." (PMID 40136656, 2025). "For example, studies have reported that elevated levels of inflammatory cytokines, such as interleukin-6 and tumour necrosis factor-alpha, are associated with endothelial dysfunction and may predispose patients to OH during hemodialysis." (PMID 41281282, 2025). "Among the many cytokines, interleukin (IL)-6 is usually produced after infection, and elevated IL-6 levels may cause multisystemic damage, such as disseminated intravascular coagulation, endothelial dysfunction, and myocardial impairment." (PMID 40136690, 2025). "The common genetic mutation of MELAS (3243 A > G) causes complex I deficiency causing muscle fatigue and is complicated by endothelial dysfunction with atherogenic and pro-inflammatory properties including upregulation of inflammatory genes, such as IL-6 and TNF-α." (PMID 40142856, 2025). "IL-6 can contribute to vascular hypertrophy and endothelial dysfunction caused by angiotensin II." (PMID 38846493, 2024). "The upregulation of inflammatory cytokines, such as TNF-α and IL-6, causes endothelial dysfunction, manifested by the increased production of adhesion molecules, enhanced vascular permeability, and promotion of endothelial cell proliferation and migration of vascular smooth muscle cells." (PMID 38666951, 2024). "Additional assessments for evaluating endothelial dysfunction involve measuring biomarkers in the blood that indicate harmful events in the heart and vessels, like the release of cytokines linked to inflammation (IL‐6 and IL‐1β)." (PMID 39040847, 2024). "Endotoxin causes increased activity of IL-6 and acid sphingomyelinase (aSMase) in HPASMCs, promotes pulmonary vasoconstriction, induces endothelial dysfunction and enhances the contractile response to serotonin, ultimately leading to PH in patients with acute respiratory distress syndrome (ARDS)." (PMID 37449201, 2023). "In vitro exposure of endothelial cells to flavoring additives commonly used in tobacco products induced endothelial dysfunction characterized by a loss of nitric oxide production, with several of the additives upregulating proinflammatory interleukin 6, even at the lowest dilutions tested." (PMID 38017396, 2023). "Dialytic protein loss may reflect generalized endothelial dysfunction and is independently predicted by the D/P creatinine and the appearance rate of IL-6, a marker of local peritoneal inflammation." (PMID 37833387, 2023). "Proinflammatory mediators including TNF-α and IL-6, in addition to ROS, are known to increase the risk of endothelial dysfunction by inhibiting the bioactivity of NO and eNOS and by upregulating the expression of many atherosclerotic factors via the NF-κB pathway." (PMID 38068901, 2023). "The biological mechanisms underlying this association are thought to include mainly oxidative stress, systemic inflammation (e.g., interleukin-1β, tumor necrosis factor-α, interleukin-6, and C-reactive protein), and endothelial dysfunction caused by prolonged high SUA levels." (PMID 37004085, 2023). "Increased levels of TNF-α and IL-6, through increased production of reactive oxygen species, may lead to endothelial dysfunction with an increased risk of CVDs and less optimal overall outcomes." (PMID 35683564, 2022).
endothelial dysfunction (continued). "Although the cause of endothelial dysfunction in KD remains unknown, endothelialactivation and endothelial dysfunction are presumably due to increased cytokineproduction (e.g., IL-1, IL-6, and TNF) by immune effector cells via theNF-κB pathway." (PMID 39076622, 2022). "Our recent study shows that NPR1 deficiency causes endothelial dysfunction marked by augmented interleukin 6 and interleukin 8, elevated reactive oxygen species (ROS) production, and decreased endothelial nitric oxide synthase (eNOS) and nitric oxide (NO) levels in vitro and in vivo." (PMID 36293483, 2022). "This phenomenon of ergothioneine could effectively regulate endovascular inflammation caused by endothelial dysfunction and reduce the release of pro-inflammatory factors, including interleukin-6 (IL-6), IL-1β, and TNF-α." (PMID 36160418, 2022). "A possible mechanism for these findings is the secretion of inflammatory factors from central or visceral adipose tissue such as tumor necrosis factor-alpha and interleukin-6 which causes endothelial dysfunction at the glomerular level, resulting in an increase in urine albumin excretion." (PMID 34461808, 2021). "Besides, hypertension is associated with endothelial dysfunction and a pro-inflammatory state, which includes higher levels of Ang II, chemokines, and cytokines, including interleukin-6 (IL-6) and tumor necrosis factor-α (TNF-α)." (PMID 34012410, 2021). "Besides, endothelial dysfunction and vascular remodeling caused by IL-6, TGF-β, TNF-α, EGFR, and VEGFA are also some of the core features of CVD." (PMID 32454875, 2020). "Consistently, IL-6 deficiency mice are protected against Ang II-mediated endothelial dysfunction." (PMID 28484449, 2017). "In patients with diabetic foot lower plasma levels of adiponectin and higher plasma levels of IL-6 and resistin could be linked to endothelial dysfunction and progressive arterial stiffening." (PMID 28056981, 2017). "Within a longitudinal study we for the first time show that inflammation as measured by IL-6 and a biomarkers-based inflammation score and endothelial dysfunction as measured by VCAM-1, is associated with LVMI worsening over time in patients across the whole spectrum of pre-dialysis CKD." (PMID 26398099, 2015). "The aim of the present work was to examine whether reduced endurance running capacity in IL-6−/− mice is linked to impaired maximal oxygen uptake (V′O2max), decreased glucose tolerance, endothelial dysfunction or other mechanisms." (PMID 24533077, 2014). "The degree of impairment associated with 28-day infusion of 400 ng/kg/min Ang II was very similar to the degree of endothelial dysfunction produced with either 14 or 28 day infusion of 1000 ng/kg/min Ang II, both of which were associated with increases in IL-6 and vascular macrophage levels." (PMID 25400581, 2014). "Data from vascular tissue suggest that changes in expression of NADPH oxidase and IL-6 might contribute to the observed endothelial dysfunction in old IL-10-deficient mice." (PMID 24400151, 2013). "In addition, the relationship between vitamin D deficiency and endothelial dysfunction was confirmed also investigating potential biochemical markers, such as interleukin (IL)-6 and circulating endothelial progenitor cells." (PMID 24459602, 2013). "Of the markers of chronic inflammation (CRP, and IL-6) and endothelial dysfunction (sICAM-1), sST2 showed a significant association after age-sex adjustment only with sICAM-1, with a relative increase of 4.9% (2.5% to 7.3%, p = 0.0001) per SD increase in log sST2." (PMID 23112853, 2012). "Several shared mechanisms, including chronic inflammation, activation of the renin–angiotensin–aldosterone system (RAAS), and endothelial dysfunction, might explain the association between pre-existing uncontrolled BP, high IL-6, and IL-17 concentrations, and long COVID in patients undergoing HD." (PMID 38424126, 2024).